Y_RNA (Y RNA )
Gene: Miscellaneous RNA gene on chromosome 21 (7,474,394 to 7,474,494, forward strand). Ensembl gene ENSG00000274484.
Homologues: Orthologues: chimpanzee Y_RNA (100% identical). Paralogues in human: Y_RNA (100% identical), Y_RNA (86% identical), RNY3 (85% identical), Y_RNA (85% identical), RNY3P1 (84% identical), Y_RNA (84% identical), RNY3P11 (83% identical), Y_RNA (83% identical), Y_RNA (82% identical), Y_RNA (81% identical), RNY3P3 (80% identical), Y_RNA (80% identical), and 95 more.